KRT4 (keratin 4)
Description:
Structural component of intermediate filaments in mucosal stratified squamous epithelia. Forms heteropolymers with the type I keratin KRT13, assembling into keratin intermediate filament networks that provides structural integrity and mechanical stability of the mucosal epithelium.
Synonyms: CK-4; K4; CYK4; CK4; WSN1
Tractability: PROTAC: ubiquitination databases record sites on it.
Target class: Structural protein
Gene: Protein-coding gene on chromosome 12 (52,806,549 to 52,814,116, reverse strand). Ensembl gene ENSG00000170477.
Subcellular location (Human Protein Atlas): Intermediate filaments
Pathways (Reactome):
Developmental Biology: Formation of the cornified envelope; Keratinization
Gene Ontology:
Molecular function: protein binding; structural constituent of skin epidermis
Biological process: cytoskeleton organization; epithelial cell differentiation; intermediate filament organization; keratinization; negative regulation of epithelial cell proliferation
Cellular component: cell surface; intermediate filament cytoskeleton; keratin filament; nucleus; cytosol; intermediate filament
Genetic constraint (gnomAD): Loss-of-function variants: 45 observed, 53 expected, observed/expected ratio (o/e) 0.85, 90% interval 0.67 to 1.09. The upper end of that interval is the gene's LOEUF score, 1.09, which puts it in group 4 of 6, group 1 being the genes least tolerant of losing a copy. Missense variants: 646 observed, 686.28 expected, observed/expected ratio (o/e) 0.94, 90% interval 0.88 to 1. Synonymous variants: 254 observed, 268.94 expected, observed/expected ratio (o/e) 0.94, 90% interval 0.85 to 1.05.
Homologues: Orthologues: chimpanzee KRT4 (99% identical), macaque KRT4 (97% identical), pig KRT4 (87% identical), guinea pig KRT4 (84% identical), mouse Krt4 (82% identical), rat Krt4 (81% identical), tropical clawed frog krt78.6 (60% identical). Paralogues in human: KRT3 (69% identical), KRT76 (67% identical), KRT5 (67% identical), KRT6A (64% identical), KRT6B (64% identical), KRT1 (63% identical), KRT6C (63% identical), KRT75 (62% identical), KRT79 (62% identical), KRT2 (62% identical), KRT73 (61% identical), KRT77 (60% identical), and 56 more.